MADCAM1 (mucosal vascular addressin cell adhesion molecule 1)
Description:
Cell adhesion leukocyte receptor expressed by mucosal venules, helps to direct lymphocyte traffic into mucosal tissues including the Peyer patches and the intestinal lamina propria. It can bind both integrin alpha-4/beta-7 and L-selectin, regulating both the passage and retention of leukocytes. Isoform 2, lacking the mucin-like domain, may be specialized in supporting integrin alpha-4/beta-7-dependent adhesion strengthening, independent of L-selectin binding.
Synonyms: MACAM1
Tractability: Antibody: a drug acting on it is in phase 2 or 3 trials; its Gene Ontology location is reachable by antibodies, with high confidence; UniProt predicts a signal peptide or a membrane-spanning region.
Target class: Adhesion
Gene: Protein-coding gene on chromosome 19 (489,176 to 505,343, forward strand). Ensembl gene ENSG00000099866.
Subcellular location: Membrane
Pathways (Reactome):
Extracellular matrix organization: Integrin cell surface interactions
Immune System: Immunoregulatory interactions between a Lymphoid and a non-Lymphoid cell
Gene Ontology:
Molecular function: integrin binding involved in cell-matrix adhesion
Biological process: cell-matrix adhesion; heterotypic cell-cell adhesion; integrin-mediated signaling pathway; leukocyte tethering or rolling; receptor clustering; cell adhesion; immune response; positive regulation of leukocyte migration; signal transduction; cell-cell adhesion; positive regulation of lymphocyte migration
Cellular component: membrane; plasma membrane
Genetic constraint (gnomAD): Loss-of-function variants: 19 observed, 13.17 expected, observed/expected ratio (o/e) 1.44, 90% interval 0.99 to 1.9. The synonymous counts are far from expectation, so gnomAD's model fits this gene poorly and the ratio says little. Missense variants: 514 observed, 397.83 expected, observed/expected ratio (o/e) 1.29, 90% interval 1.2 to 1.39. Synonymous variants: 268 observed, 185.53 expected, observed/expected ratio (o/e) 1.44, 90% interval 1.31 to 1.6.
Homologues: Orthologues: chimpanzee MADCAM1 (96% identical), macaque MADCAM1 (80% identical), dog MADCAM1 (48% identical), mouse Madcam1 (46% identical), rat Madcam1 (36% identical).
Diseases named in the same sentence as MADCAM1 in open-access papers:
MADCAM1 is named in the same sentence as 81 diseases in open-access papers, as found by Europe PMC text mining. Sharing a sentence is not in itself a finding about the gene and the disease. The quoted sentences say what the papers report.
colitis (31 papers, 2005 to 2025). Inflammation of the colon. "In the present study, the injection of a MAdCAM-1 inhibitory mAb into T cell-specific Rap1-deficient mice prevented the development of colitis." (PMID 32764635, 2020). "This knowledge is mainly derived from animal experiments using antibodies directed against MAdCAM-1 or its associated homing receptor α4β7 in naïve mice or in colitis models." (PMID 31114574, 2019). "The effect of MAdCAM-1 blockade on the microbiota and colitis severity in IL-10−/− cohoused siblings supports a causal effect, induced by the resultant luminal SIgA deficit, expansion of a dysbiotic flora, barrier breach, and possible systemic sepsis as reflected by hypothermia." (PMID 34433904, 2022). "The MAdCAM-1 blockade model shows a dynamic process whereby effects on plasmablast recruitment result in converse effects in peripheral blood and LP, eventually leading to hypothermia, weight loss, and aggravated colitis." (PMID 34433904, 2022). "Lactobacillus plantarum and its excreted peptide STp have shown stimulation of skin-homing markers in vitro, such as cutaneous lymphocyte-associated antigen (CLA), and a decrease in MadCAM-1 and α4β7 integrin expression in colonic mucosa in a mouse model of colitis." (PMID 27820846, 2016). "Next, we sought to determine whether T567E ezrin or AcLOK affected the adhesion cascade on MadCAM-1 under shear flow in Rap1-deficient TEM cells derived from LNs of mice developing colitis, including TH17 and TH1 cells." (PMID 26634692, 2015). "For example, angiotensin II type 1 receptor blockade can modulate TNF-α-induced MAdCAM-1 expression by inhibiting NF-κB nuclear translocation, thereby ameliorating colitis." (PMID 41301753, 2025). "MAdCAM-1 expression is increased in models of colitis, and colitis severity can be reduced through blockade or neutralization of α4β7." (PMID 39937862, 2025). "Meanwhile, another study revealed that nicotine treatment attenuates colitis through downregulating B2 integrin or MAdCAM-1 expression on the inflamed colonic microvessels." (PMID 38790962, 2024). "Further studies are required to determine where α4β7 expressing monocytes and MAdCAM-1 are interacting to prime the neutrophils that subsequently enter the brain in this model of colitis." (PMID 35379260, 2022). "We were unable to block the reduced anxiety-like behavior by treating animals with either anti-α4β7 or anti-MAdCAM-1 antibodies after initiating colitis." (PMID 35379260, 2022). "The expression of RA-regulated gut homing molecules including α4β7 integrin, and CCR9, along with MADCAM1 were all reduced in colitis mice revealing compromised immunity due to reduced RA signaling." (PMID 35889745, 2022). "It remains difficult to reconcile the therapeutic effect of α4β7-MAdCAM-1 blockade seen in patients treated with VDZ or ontamalimab (anti-MAdCAM-1) with the hastening effect of a parallel intervention on IL-10−/− colitis." (PMID 34433904, 2022). "This is in line with previous reports and with our analysis showing an increase in ICAM-1 and MAdCAM-1 levels on endothelial cells throughout DSS-induced colitis." (PMID 33932356, 2021). "In a mouse model of colitis, nicotine suppressed the expression of mucosal addressin cell-adhesion molecule-1 (MAdCAM-1) protein in the mucosal venules of the inflamed colon." (PMID 33572734, 2021). "Increased expression of MAdCAM-1 in the endothelium of the inflamed colon of rats induced by peptidoglycan-polysaccharide, and subsequent attenuation of colitis by anti-MAdCAM-1 antibody, imply a vital role of this molecule in the development of colitis." (PMID 32354192, 2020). "This was explained by a decrease of MAdCAM-1 expression on endothelial cells in the gut of DSS-induced colitis, possibly through a direct effect of nicotine on the vascular endothelium." (PMID 32268498, 2020). "For example, expression of MAdCAM-1 is upregulated in different animal models of colitis as well as in EAE." (PMID 31114574, 2019).
colitis (continued). "Blockade of MAdCAM-1 in disease models, and therefore inhibition of immune cell infiltration to inflammatory sites, resulted in attenuated colitis." (PMID 31114574, 2019). "This notion is supported by several observations that show that antibodies directed against either MAdCAM-1, or its lymphocyte ligand, the α4β7 integrin will significantly attenuate several indices of injury in experimental models of colitis." (PMID 15694007, 2005). "In the setting of IBD, the expression of ECAMs like ICAM-1, VCAM-1, and MAdCAM-1 is observed in experimental models of colitis, and also within the inflamed human colon in Crohn's disease and ulcerative colitis." (PMID 15694007, 2005). "This notion is well supported by several reports that show that antibodies directed against either MAdCAM-1, or its lymphocyte ligand, the α4β7 integrin, will significantly attenuate several indices of gut damage in experimental models of colitis." (PMID 16259632, 2005). "β7 deficiency and MAdCAM-1 blockade specifically depleted antibody secreting cells (ASC) (not T cells) from the colonic LP, leading to a fecal pan-immunoglobulin deficit, severe colitis, and alterations of microbiota composition." (PMID 34433904, 2022). "We demonstrate that β7 deficiency and MAdCAM-1 blockade lead to colonic B cell/ASC deficits, fecal Ig deficit, and hastening of colitis, associated with major changes in microbiota composition, distinct from those induced by colitis alone." (PMID 34433904, 2022). "VCAM-1 antagonists proved superior to ICAM-1 and MAdCAM-1 blockade in the murine model of DSS colitis, and the monoclonal anti-α4 integrin antibody natalizumab has been successfully used for blockade of VCAM-1-dependent leukocyte trafficking in patients with active CD." (PMID 34017333, 2021). "Therefore, we conclude that the change in endothelial MAdCAM-1 levels is necessary for the observed beneficial effect of the optogenetic sympathetic activation on DSS-induced colitis." (PMID 33932356, 2021). "Finally, we sought to establish, at the functional level, that the effects of the optogenetic activation on the DSS-induced colitis are MAdCAM-1 dependent." (PMID 33932356, 2021). "Inhibiting this Madcam1 interaction with T cells is known to ameliorate symptoms of colitis." (PMID 34831429, 2021). "On the other hand, a relevant report established that VCAM-1 plays a central role in leukocyte recruitment in colitis and blockade of this adhesion molecule has higher therapeutic effect than immune neutralization of ICAM-1 or MAdCAM-1 in colitis experimental model." (PMID 22073270, 2011). "The functional significance of increased expression of MAdCAM-1 in IBD is supported by several reports which demonstrate that immunoneutralization of either MAdCAM-1 or its lymphocyte ligand, the α4β7 integrin, attenuate inflammation and mucosal damage in a variety of animal models of colitis." (PMID 15694007, 2005). "Based on these results, it is apparent that an improved understanding of the mechanisms regulating ECAM expression, especially MAdCAM-1, might help to design improved therapies for colitis." (PMID 15694007, 2005). "Based on these findings, it is apparent that a better understanding of the mechanisms regulating ECAM expression, especially that of MAdCAM-1, might help to devise improved therapies for colitis." (PMID 16259632, 2005). "The functional significance of increased appearance of MAdCAM-1 in IBD is supported by several reports which show that immunoneutralization of either MAdCAM-1 or its ligand, the α4β7 integrin, attenuate inflammation and mucosal damage in animal models of colitis." (PMID 16259632, 2005). "However, once colitis is fully established, it is plausible that further inflammation may arise by newly recruited T cells that migrate via the α4β7 integrin/MAdCAM-1 axis." (PMID 37872166, 2023).
colitis (continued). "We were not able to block the reduced anxiety-like behavior by treating animals with anti-α4β7 or anti-MAdCAM-1 antibodies after initiating colitis, suggesting that elevations in central cytokines earlier in the course of disease may have already initiated the changes in the CNS." (PMID 35379260, 2022). "In addition, the level of Madcam1 mRNA was also reduced in the colon of colitis mice." (PMID 35889745, 2022). "Interestingly, MAdCAM-1 was also found to be upregulated on inflamed venules in chronic inflammatory diseases, for example in the intestine in colitis and in choroid plexus epithelium during experimental autoimmune encephalomyelitis (EAE), an animal model of multiple sclerosis (MS)." (PMID 31114574, 2019). "However, since monoclonal antibodies directed against other ECAMs, particularly VCAM-1, can as well reduce disease activity in animal models of colitis, the literature suggests that MAdCAM-1 is probably necessary, but insufficient for the maximal penetrance of experimental and clinical IBD." (PMID 15694007, 2005). "However, since monoclonal antibodies directed against other ECAMs, particularly VCAM-1, can as well reduce disease activity in colitis models, the literature suggests that MAdCAM-1 is probably necessary, but insufficient for the maximal penetrance of experimental and probably also clinical IBD." (PMID 16259632, 2005). "Lactobacillus plantarum treatment ameliorated histological damage and decreased the expression of adhesion molecules MAdCAM-1, ICAM-1, and α4β7 in IL10−/− colitis mice." (PMID 41301753, 2025). "Pre-clinical trials with the murine anti-MAdCAM-1 antibody MECA-367 demonstrated reduced lymphocyte recruitment to the gut and reduction of inflammation in the T cell transfer colitis model in Scid mice." (PMID 34017333, 2021). "In murine colitis induced with sodium dextran sulfate (DSS), the P. freudenreichii DHNA metabolite attenuated the expression of mucosal addressin cell adhesion molecule 1 (MAdCAM-1), which favors leucocyte infiltration." (PMID 40563526, 2025). "In DSS colitis, FXR activation prevents decreases in more anti-inflammatory splenic dendritic cells and T-regulatory cells, while inhibiting increases in pro-inflammatory chemokines like Madcam1 in pro-inflammatory cells." (PMID 34831429, 2021). "Blockade of MAdCAM-1 by anti-MAdCAM-1-antibody showed very modest beneficial effects in different models of experimental colitis as well as in some phases of progressive, non-remitting EAE." (PMID 31114574, 2019). "In the same study, chronic administration of anti-VCAM-1 antibody, but not anti-ICAM-1 or anti-MAdCAM-1, resulted in significant attenuation of colitis in terms of disease activity index, colon length, ratio of colon weight to length, and myeloperoxidase activity." (PMID 22073270, 2011). "Additionally, it was observed that a tellurium-based compound could preserve the colonic epithelium integrity in the DSS colitis mouse model by preventing the migration of a4β7+ macrophages to the colon and the adhesion of MLN cells to MadCAM-1 both in vitro and in vivo." (PMID 35163775, 2022). "Furthermore, an anti-MAdCAM-1 antibody, which does not bind CD103, also hastened colitis in adult IL-10−/− mice." (PMID 34433904, 2022).
inflammatory bowel disease (30 papers, 2005 to 2025). A spectrum of small and large bowel inflammatory diseases of unknown etiology. "MAdCAM-1 has been reported as one of the nine groups of susceptibility loci shared by inflammatory bowel disease and autoimmune liver disease." (PMID 41301753, 2025). "Soluble MAdCAM-1 (sMAdCAM-1) levels in serum have been previously associated with gut inflammation occurring during inflammatory bowel disease and have been suggested as a biomarker for tracking effectiveness of therapy." (PMID 33828560, 2021). "Cytokine mediated induction of the mucosal addressin cell adhesion molecule-1(MAdCAM-1) expression is associated with the onset and progression of inflammatory bowel disease (IBD)." (PMID 15694007, 2005). "Nkx2-3 as a transcriptional regulator of MAdCAM-1 controls vascular patterning in visceral lymphoid tissues in mice, and has been identified as a susceptibility factor for inflammatory bowel diseases in humans, associated with lymphoid neogenesis in the inflamed intestines." (PMID 30891037, 2019). "Our results here may support previous assumptions that MAdCAM-1 expression might be one of the causes of lymphocyte-mediated liver disease, like autoimmune hepatitis and primary sclerosing cholangitis, which complicate inflammatory bowel disease." (PMID 17868448, 2007). "Significant upregulation of CCR9, CCL25, and MAdCAM-1 suggests increased lymphocyte trafficking to the gut, similar to mechanisms described in human inflammatory bowel disease." (PMID 40564263, 2025). "We previously determined that vedolizumab, an α4β7 antagonist employed as a therapeutic for inflammatory bowel diseases (IBDs), can suppress the formation of MAdCAM-1 -generated TRM cells." (PMID 40747422, 2025). "MAdCAM-1 is upregulated in inflammatory bowel diseases (IBDs), and blocking the α4β7/MAdCAM-1 interaction with vedolizumab, a humanized monoclonal antibody to α4β7, is an effective therapeutic for IBDs." (PMID 39903521, 2025). "α4β7 integrin expressed on gut lymphocytes contributes to the pathogenesis of inflammatory bowel disease via interaction with endothelial MAdCAM-1." (PMID 38997751, 2024). "Previous research suggests that, while adhesion molecules like ICAM-1 and MAdCAM-1 also contribute to the treatment of inflammatory bowel diseases, selectively blocking VCAM-1 appears to offer higher potential efficacy in managing these conditions." (PMID 38660311, 2024). "The interaction between integrin α4β7 and mucosal vascular addressin cell-adhesion molecule-1 (MAdCAM-1) facilitates the adhesion of circulating lymphocytes to the surface of high endothelial venules in inflammatory bowel diseases (IBDs)." (PMID 38003252, 2023). "Differentiation of TRM-like cells was reduced by MAdCAM-1 antagonists developed to treat inflammatory bowel diseases." (PMID 36897929, 2023). "Madcam1 has been linked previously to TNF-α and is an important player in the development of inflammatory bowel diseases, but only few studies describe Madcam1 in the context of retinopathies, in contrast to other adhesion molecules like Vcam1." (PMID 36371417, 2022). "Increases in MAdCAM-1 expression have been reported in diseases underpinned by severe inflammation including inflammatory bowel disease, diabetes and cholangitis." (PMID 35008227, 2021). "Mucosal addressin cell adhesion molecule-1 (MAdCAM-1) and its ligand, α4β7 integrin, are involved in inflammatory bowel diseases and liver dysfunctions, which occur more frequently in PSO and LP." (PMID 34827121, 2021). "Targeting interactions between α4β7 integrin and endothelial adhesion molecule MAdCAM-1 to inhibit lymphocyte migration to the gastrointestinal tract is an effective therapy in inflammatory bowel disease (IBD)." (PMID 34561227, 2021). "MAdCAM-1 executes critical roles in different inflammatory diseases, e.g., in inflammatory bowel disease (IBD)." (PMID 34830018, 2021).
inflammatory bowel disease (continued). "Monoclonal antibodies against MADCAM1 and are showing clinical benefits in inflammatory bowel disease [Sheridan, 2014], and hence based on our genetic results presented here, investigation of the effects of these drugs in T1D is worth considering." (PMID 25371288, 2014). "With respect to inflammatory bowel disease, MAdCAM-1 appears to be necessary for lymphocyte homing to mucosa associated lymphoid tissue." (PMID 15694007, 2005). "MAdCAM-1 is constitutively expressed by intestinal endothelial cells, and its expression is upregulated on inflamed venules in chronic inflammatory diseases (e.g., inflammatory bowel disease) and induced by TNF-α and IL-1β." (PMID 38338944, 2024). "In normal biology and especially during active inflammatory bowel disease, MAdCAM-1 may be essential to the lymphocyte homing to mucosa associated lymphoid tissue (MALT)." (PMID 16259632, 2005). "It has been confirmed that MAdCAM-1 is an important target for the therapeutic treatment of chronic inflammatory bowel disease (IBD)." (PMID 28700735, 2017). "Recently it was reported that MAdCAM-1 was expressed in the liver portal region in autoimmune hepatitis, and MAdCAM-1 mediated adhesion might provide a basis for hepatic recruitment of mucosal lymphocytes, (at least in inflammatory bowel disease complicated by liver disease)." (PMID 17868448, 2007). "This suggests that the interaction between MAdCAM-1 and α4β7 is closely related to the recruitment of lymphocytes to the intestine in chronic inflammatory diseases, and blocking their binding could be a relevant therapeutic target for inflammatory bowel disease patients." (PMID 41301753, 2025). "Two recombinant humanized anti-MAdCAM-1 mAbs, PF-00547659 and SHP64/Ontamlimab, are used for treating patients with inflammatory bowel disease (ulcerative colitis and Crohn’s disease)." (PMID 39518902, 2024). "β7 integrin/MAdCAM-1-mediated homing of immune cells contributes to the development of immunogenic and tolerogenic immune responses in the gastrointestinal tract and has been shown to promote inflammatory bowel diseases (IBD)." (PMID 31636620, 2019). "The expression of MAdCAM-1 on gut endothelial was increased in sites of mucosal inflammation in patients with inflammatory bowel disease, but not IBS controls." (PMID 35844499, 2022).